RAB26 (RAB26, member RAS oncogene family)
Description:
The small GTPases Rab are key regulators of intracellular membrane trafficking, from the formation of transport vesicles to their fusion with membranes. Rabs cycle between an inactive GDP-bound form and an active GTP-bound form that is able to recruit to membranes different set of downstream effectors directly responsible for vesicle formation, movement, tethering and fusion (By similarity). RAB26 mediates transport of ADRA2A and ADRA2B from the Golgi to the cell membrane. Plays a role in the maturation of zymogenic granules and in pepsinogen secretion in the stomach. Plays a role in the secretion of amylase from acinar granules in the parotid gland (By similarity).
Synonyms: V46133
Tractability: Small molecule: a structure with a bound ligand is known. Antibody: its Gene Ontology location is reachable by antibodies, with medium confidence.
Gene: Protein-coding gene on chromosome 16 (2,140,803 to 2,154,165, forward strand). Ensembl gene ENSG00000167964.
Subcellular location: Golgi apparatus membrane; Cytoplasmic vesicle, secretory vesicle membrane
Subcellular location (Human Protein Atlas): Centrosome; Plasma membrane; Cell Junctions; Cytosol; Vesicles
Pathways (Reactome):
Metabolism of proteins: RAB geranylgeranylation
Gene Ontology:
Molecular function: G protein activity; GMP binding; GTP binding; protein binding; GTPase activity
Biological process: exocrine system development; Golgi to plasma membrane protein transport; regulated exocytosis; regulation protein catabolic process at presynapse; regulation of exocytosis
Cellular component: Golgi membrane; synaptic vesicle membrane; plasma membrane; secretory granule membrane; transport vesicle membrane
Genetic constraint (gnomAD): Loss-of-function variants: 39 observed, 31.76 expected, observed/expected ratio (o/e) 1.23, 90% interval 0.95 to 1.6. The synonymous counts are far from expectation, so gnomAD's model fits this gene poorly and the ratio says little. Missense variants: 468 observed, 321.96 expected, observed/expected ratio (o/e) 1.45, 90% interval 1.35 to 1.57. Synonymous variants: 192 observed, 131.84 expected, observed/expected ratio (o/e) 1.46, 90% interval 1.29 to 1.64.
Homologues: Orthologues: macaque RAB26 (93% identical), chimpanzee RAB26 (88% identical), dog RAB26 (88% identical), mouse Rab26 (87% identical), pig RAB26 (87% identical), guinea pig RAB26 (85% identical), rat Rab26 (84% identical), tropical clawed frog rab26 (76% identical), zebrafish RAB26 (58% identical). Paralogues in human: RAB37 (57% identical), RAB10 (39% identical), RAB8A (39% identical), RAB8B (39% identical), RAB13 (36% identical), RAB44 (36% identical), RASEF (36% identical), RAB1B (35% identical), RAB27A (34% identical), RAB3B (34% identical), RAB1A (34% identical), RAB6A (34% identical), and 56 more.
Diseases named in the same sentence as RAB26 in open-access papers:
RAB26 is named in the same sentence as 30 diseases in open-access papers, as found by Europe PMC text mining. Sharing a sentence is not in itself a finding about the gene and the disease. The quoted sentences say what the papers report.
breast carcinoma (7 papers, 2019 to 2025). "At the same time, by interacting with autophagy-related 16-like 1 (ATG16L1), RAB26 directs synaptic vesicles to undergo autophagy and inhibits migration and invasion of invasive breast cancer cells." (PMID 40821113, 2025). "Over-expression of Rab26 inhibits cell migration and invasion, while Rab26 knockdown significantly promotes the migration and invasion of breast cancer cells." (PMID 33731709, 2021). "In this study, we found that the expression of Rab26 is suppressed in the aggressive breast cancer cells as compared to the levels in non-invasive breast cancer cells." (PMID 33731709, 2021). "Here MDA-MB-231 cells expressing Rab26 were used to verify Rab26 mediating autophagy process in breast cancer cells." (PMID 33731709, 2021). "Since Rab26 is lower expressed in the high-aggressive breast cancer cells, we examined the possibility that over-expression of Rab26 will inhibit the migration and invasion of the highly invasive breast cancer cells." (PMID 33731709, 2021). "Mechanistically, our results uncover that Rab26 regulates the autophagic degradation of phosphorylated Src to inhibit the invasion and migration of breast cancer cells, indicating that Rab26 is a novel tumor suppressor for breast cancer." (PMID 33731709, 2021). "Further investigations revealed that Rab26 regulates the degradation of the active phospho-Src kinase through autophagic pathway, thus inhibiting cell adhesion, migration, and invasion of breast cancer cells." (PMID 33731709, 2021). "In this study, we found Rab26 inhibits migration/invasion through mediating the autophagic degradation of active Src, suggesting a unique function of Rab26 and a different regulatory mechanism from other Rab proteins in breast cancer cells." (PMID 33731709, 2021). "Taken together, Rab26 inhibits the migration and invasion of higher-invasive breast cancer cells, and Rab26 depletion conversely promotes the migration and invasion of lower-invasive breast cancer cells." (PMID 33731709, 2021). "Survival analysis using breast cancer datasets showed that breast cancer patients with higher Rab26 expression are correlated with a significantly higher probability of overall survival." (PMID 33731709, 2021). "In this study, we found that Rab26 is expressed at higher level in lower-invasive breast cancer cell lines, and its expression is suppressed in invasive breast cancer cells." (PMID 33731709, 2021). "Our results strengthen that another trafficking pathway of Src, namely autophagic degradation of Src regulated by Rab26 in breast cancer cells, which has been described in pulmonary endothelial cells." (PMID 33731709, 2021). "Our results demonstrated that Rab26 promotes autophagy in breast cancer cells, which probably due to enhance the recruitment of ATG16L1." (PMID 33731709, 2021). "In silico analysis of breast cancer clinical datasets showed that KLK6 expression inversely correlates with RAB26, RAB17, and RAB30." (PMID 30980596, 2019). "However, in breast cancer, RAB26 inhibits the migration and invasion of breast cells by mediating autophagic degradation and phosphorylation of Src." (PMID 40821113, 2025). "Finally, RAB26, the last downregulated gene significantly promotes the migration and invasion of breast cancer cells in Rab26 knockdown sample, and the protein products are important regulators of vesicular fusion and trafficking." (PMID 35163690, 2022). "In consistent with the expression pattern in the breast cancer lines, these results suggested that Rab26 may play an important role in suppressing invasive behavior of breast cancer." (PMID 33731709, 2021). "In this study, we found that the highly aggressive breast cancer cells have a lower level of Rab26 protein, and over-expression of Rab26 in these cells inhibits the migration and invasion; on the other hand, Rab26 knockdown in less aggressive breast cancer cells promotes the invasion and migration." (PMID 33731709, 2021).
breast carcinoma (continued). "Over-expression of Rab26 inhibits migration and invasion of invasive breast cancer cells." (PMID 33731709, 2021). "Some studies have found that RAB26 can affect the metastasis and invasion of breast cancer." (PMID 33490103, 2020). "Therefore, we next investigated how Rab26 regulates Src in breast cancer cells." (PMID 33731709, 2021). "On the other hand, RAB26 was novel in HCC but was newly identified as a suppressor of the migration and invasion of breast cancer cells." (PMID 35300417, 2022). "Further experiments revealed that Rab26 mediates the autophagic degradation of phosphorylated Src through interacting with ATG16L1, consequently, resulting in the suppression of the migration and invasion ability of breast cancer cells." (PMID 33731709, 2021). "Our findings demonstrated that Rab26 harnesses the same mechanism as that in non-cancer cells to regulate migration and invasion of breast cancer cells, in that Rab26 promotes the autophagic targeting and degradation of p-Src through interacting with ATG16L1." (PMID 33731709, 2021). "Through systematically examination of the mRNA levels of Rab proteins in breast cancer cell lines (data not shown), we found the expression level of Rab26 transcript is relatively lower in all eight breast cancer cell lines compared with the normal breast tissue cell line MCF10A." (PMID 33731709, 2021).
lung carcinoma (3 papers, 2019 to 2024). "For example, RAB1b is reported to be involved in sorafenib-resistance of HCC, and high expression of RAB26 promotes the cisplatin-based drug resistance in lung cancer." (PMID 39101146, 2024). "One research group recently determined that Ras-related protein Rab-26 (RAB26) was involved in SNRPB-mediated cell growth and metastasis in lung cancer." (PMID 33289700, 2020). "Building on our findings that SNRPB co-expressed with RAB26 in NSCLC cell lines, we accessed the UALCAN26 and cBioPortal27 datasets to assess the relationship between expression of the SNRPB gene and RAB26 gene in clinical lung cancer samples." (PMID 31511502, 2019).
colon cancer (2 papers, 2017 to 2024). "In two colon cancer cell lines, we observed upregulation of other exocytic RABs including RAB3B, RAB26, and RAB27A as a result of RAB3C overexpression." (PMID 28784136, 2017).
glioma (2 papers, 2020 to 2023). A benign or malignant brain and spinal cord tumor that arises from glial cells (astrocytes, oligodendrocytes, ependymal cells). "Previous studies have shown that some Rab proteins such as Rab1a, Rab21, and Rab26 are closely associated with the development and progression of many tumors, including glioma." (PMID 36922509, 2023). "This study provides new insights in the PLEKHG5/RAB26 signalling within U251-MG cells, which suggests potential therapeutic strategies in other glioma cells and further in primary GBM." (PMID 33318498, 2020).
non-small cell lung carcinoma (2 papers, 2022 to 2025). A group of at least three distinct histological types of lung cancer, including non-small cell squamous cell carcinoma, adenocarcinoma, and large cell carcinoma. "Small nuclear ribonucleoprotein polypeptides B and B' (SNRPB) may regulate the tumorigenic potential of non-small cell lung cancer by modulating RAB26 expression, not by relying on RAB26's autophagic function." (PMID 40821113, 2025).
coccidiosis (1 paper, 2025). A parasitic infection caused by Coccidia. "The involvement of Rab proteins, specifically RAB3A and RAB26, in the context of coccidiosis, has not been widely studied." (PMID 41408150, 2025).
diabetes mellitus (1 paper, 2023). A metabolic disorder characterized by abnormally high blood sugar levels due to diminished production of insulin or insulin resistance/desensitization. "Since Rab26 is involved in insulin secretion, the expression of Rab26 may be related to diabetes mellitus." (PMID 37289842, 2023).
ductal carcinoma (1 paper, 2021). "IHC analysis revealed that both normal tissues and cancer tissues have Rab26 staining signals, especially, Rab26 is preferentially expressed in the ductal carcinoma, and comparatively lower staining signal was observed in the metastatic invasive ductal cancer." (PMID 33731709, 2021).
gastric cancer (1 paper, 2023). A primary or metastatic malignant neoplasm involving the stomach. "Rab26 is a transcriptional target of MIST1 that regulates the formation of exocrine secretory granules in human gastric cancer cell." (PMID 37289842, 2023).
glioblastoma (1 paper, 2020). The most malignant astrocytic tumor (WHO grade IV). "We provide substantial evidence that the PLEKHG5/RAB26 pathway is involved in the regulation of autophagy, cell proliferation, cellular morphology, apoptosis and even MGMT expression as well as promoter regulation at least in the U251-MG glioblastoma model system under investigation." (PMID 33318498, 2020).
hepatocellular carcinoma (1 paper, 2025). A malignant tumor that arises from hepatocytes. "In colorectal and hepatocellular carcinoma, EZF suppresses tumor progression via modulating pathways such as RAB26 and JNK." (PMID 40533866, 2025).
Hyperglycemia (1 paper, 2023). An increased concentration of glucose in the blood. "The mice transplanted with Ad-Rab26 islets exhibits hyperglycemia with glucose levels up to 25 mM, while the glucose levels of control mice were restored to normal." (PMID 37289842, 2023).
Infertility (1 paper, 2023). "Rab26-KO mice did not exhibit major off-target phenotypes such as lethal or infertility." (PMID 37289842, 2023).
motorneuron disease (1 paper, 2021). "Motorneurons from transgenic mice lacking the GEF Plekhg5 and in which Rab26 activation is deficient show accumulation of SV proteins and enlarged SVs that result in motorneuron disease, indicating that both Rab26 and Plekhg5 participate in the autophagy-dependent degradation of SVs." (PMID 33340068, 2021).
nasopharyngeal carcinoma (1 paper, 2022). A carcinoma arising from the nasopharyngeal epithelium. "In addition, RAB26 benefits the proliferation of nasopharyngeal carcinoma cells, which is consistent with the results of the cell proliferation assay performed in this study." (PMID 35677538, 2022).
pancreatic insulinoma (1 paper, 2023). An insulin-producing neuroendocrine tumor arising from the beta cells of the pancreas. "Deficiency of Rab26 promotes insulin secretion, which was independently verified by Rab26 knockdown in pancreatic insulinoma cells." (PMID 37289842, 2023). "Taken together, our results suggest that Rab26 serves as a negative regulator to restrict insulin secretion in pancreatic insulinoma cells and islets." (PMID 37289842, 2023). "Conversely, overexpression of Rab26 suppresses insulin secretion in both insulinoma cell lines and isolated mouse islets." (PMID 37289842, 2023). "Our results showed that depletion of Rab26 promotes insulin secretion in mice or pancreatic insulinoma cells, while overexpression of Rab26 inhibits insulin secretion in both beta cell lines and freshly isolated islets." (PMID 37289842, 2023). "Conversely, overexpression of Rab26 inhibits insulin secretion in pancreatic insulinoma cells and freshly isolated mouse islets." (PMID 37289842, 2023). "To further support our conclusion, we reduced Rab26 in mouse pancreatic insulinoma cells through CRISPR/Cas9 technique." (PMID 37289842, 2023). "To investigate how Rab26 regulates insulin secretion, we examined the subcellular location of Rab26 and the effects of its overexpression on the distribution of insulin granules in insulinoma cells." (PMID 37289842, 2023). "Importantly, Rab26 also suppressed GLP-1-stimulated insulin secretion, indicating that Rab26 restricts the glucose-stimulated insulin secretion (GSIS) in pancreatic insulinoma cells." (PMID 37289842, 2023).
pancreatitis (1 paper, 2020). Inflammation of the pancreas. "The expression of RABL2A was significantly reduced in PDAC from diabetic patients, whereas RAB26 was significantly lower in pancreatitis patients." (PMID 32759795, 2020). "The expression of RABL2A was significantly reduced in PDACs from diabetic patients, whereas RAB26 was significantly downregulated in patients with pancreatitis." (PMID 32759795, 2020). "We also found a significantly lower expression of RAB26 in PC patients with pancreatitis, which could suggest its regulation by inflammatory mediators." (PMID 32759795, 2020).
paraplegia (1 paper, 2014). Complete paralysis of the lower half of the body including both legs, often caused by damage to the spinal cord. "A further two Rabs showed strong and specific interactions with membrane traffic machinery that we did not validate because of a lack of suitable reagents: Rab26 with the spastic paraplegia proteins Spg11 and Spg15 (also found with Rab7), and Rab35 with the Rab GEF Sbf (SBF1/2 in humans)." (PMID 25453831, 2014).
prostate carcinoma (1 paper, 2025). A carcinoma that arises from epithelial cells of the prostate gland. "However, the functional role of RAB26 in prostate cancer (PCa) remains to be elucidated." (PMID 40821113, 2025).
Sepsis (1 paper, 2025). Sepsis is defined as life-threatening organ dysfunction caused by a dysregulated host response to infection. "Sepsis-induced loss of Ras-associated protein 26 (Rab26) shifts macrophages from M1 to M2, worsening GPX4 loss and increasing ferroptosis risk." (PMID 41250137, 2025). "Rab26, a member of the Rab GTPase family, is significantly downregulated in macrophages during the immunosuppressive phase of sepsis." (PMID 41250137, 2025).